MAP4 (microtubule associated protein 4)
Description:
Non-neuronal microtubule-associated protein. Promotes microtubule assembly.
Tractability: Antibody: its Gene Ontology location is reachable by antibodies, with high confidence. PROTAC: UniProt records ubiquitination sites on it; ubiquitination databases record sites on it; its protein half-life has been measured.
Gene: Protein-coding gene on chromosome 3 (47,850,678 to 48,089,295, reverse strand). Ensembl gene ENSG00000047849.
Subcellular location: Cytoplasm, cytoskeleton; Cytoplasm, cytoskeleton, microtubule organizing center
Subcellular location (Human Protein Atlas): Cytosol; Microtubules; Plasma membrane; Primary cilium; Acrosome; Basal body; Equatorial segment
Gene Ontology:
Molecular function: microtubule stabilizing activity; protein binding; RNA binding; microtubule binding; structural molecule activity; tubulin binding
Biological process: cell division; establishment of spindle orientation; microtubule cytoskeleton organization; microtubule polymerization; microtubule sliding; mitotic spindle organization; negative regulation of non-motile cilium assembly; neuron projection development; regulation of microtubule-based movement
Cellular component: axoneme; ciliary basal body; cilium; microtubule; microtubule cytoskeleton; microtubule organizing center; mitotic spindle; axon; microtubule associated complex; cytoskeleton
Genetic constraint (gnomAD): Loss-of-function variants: 60 observed, 145.21 expected, observed/expected ratio (o/e) 0.41, 90% interval 0.34 to 0.51. The upper end of that interval is the gene's LOEUF score, 0.51, which puts it in group 2 of 6, group 1 being the genes least tolerant of losing a copy. Missense variants: 2,344 observed, 2,692.9 expected, observed/expected ratio (o/e) 0.87, 90% interval 0.84 to 0.9. Synonymous variants: 858 observed, 985.13 expected, observed/expected ratio (o/e) 0.87, 90% interval 0.82 to 0.92.
Homologues: Orthologues: chimpanzee MAP4 (98% identical), macaque MAP4 (94% identical), dog MAP4 (68% identical), pig MAP4 (67% identical), rabbit MAP4 (67% identical).
Diseases named in the same sentence as MAP4 in open-access papers:
MAP4 is named in the same sentence as 83 diseases in open-access papers, as found by Europe PMC text mining. Sharing a sentence is not in itself a finding about the gene and the disease. The quoted sentences say what the papers report.
Hypertension (7 papers, 2014 to 2018). The presence of chronic increased pressure in the systemic arterial system. "Findings from previous GWAS indicated ULK4 and MAP4 genes, encoding, respectively, a Serine/Threonine-Protein Kinase and a non-neuronal microtubule-associated protein, as related to BP and hypertension." (PMID 29495593, 2018). "In this study, we conduct association analyses of hypertension status in the cohort of 1943 unrelated Mexican Americans provided by Genetic Analysis Workshop 19, focusing on exonic variants in MAP4 on chromosome 3." (PMID 27980667, 2016). "Several variants have been implicated earlier on ULK4 and MAP4 genes on chromosome 3 to be associated with hypertension." (PMID 27980663, 2016). "Marker rs218966 in gene PHF14 and rs9836027 in MAP4 significantly associated with hypertension; additionally, rare variants in SNUPN significantly associated with systolic blood pressure." (PMID 26866982, 2016). "The top 8 windows all reside in gene MAP4, which is the most susceptible gene on chromosome 3 for hypertension." (PMID 25519394, 2014). "We applied the method to analyze the MAP4 gene on chromosome 3 and have identified several haplotypes that are associated with hypertension with varying effect sizes in the range of 55 to 85 years of age." (PMID 25519413, 2014).
ovarian carcinoma (7 papers, 2007 to 2025). A malignant neoplasm originating from the surface ovarian epithelium. "There is a significant association between high MAP4 expression and the presence of residual tumours in ovarian cancer." (PMID 38341398, 2024). "MAP4 expression was significantly associated with ovarian cancer histological subtype (P < 0.001), stage (P = 0.001), grade (P < 0.001) and residual tumour (P = 0.005)." (PMID 30737623, 2019). "An association between MAP4 and paclitaxel resistance has been observed in different cancer types including ovarian cancer." (PMID 30737623, 2019). "A recent study suggested an association between Syk and MAP4 in ovarian cancer cells." (PMID 30737623, 2019). "Inhibiting the phosphorylation of MAP4 increases microtubule stability, which enhances paclitaxel sensitivity in ovarian cancer cells." (PMID 41360780, 2025). "Studies have shown that stabilization of microtubules by inhibiting the phosphorylation of MAP4 enhances the sensitivity of ovarian cancer cells to paclitaxel." (PMID 38341398, 2024). "MAP4, Syk, and calpain-1 are interrelated and interact to regulate ovarian cancer cell proliferation." (PMID 38341398, 2024). "MAP4 showed predominant staining in the cytoplasm of the ovarian cancer cells with membranous staining apparent." (PMID 30737623, 2019). "Researchers have found that phosphorylation of MAP4 could regulate microtubule stability and paclitaxel sensitivity, which could be used as a strategy to improve primary therapy for ovarian cancer." (PMID 35845140, 2022). "The drug sensitivity profile of ovarian cancer paclitaxel-resistant sublines parallels the regulation of MAP4 modification: MAP4 phosphorylation and dissociation from microtubules decrease the sensitivity of paclitaxel-resistant ovarian cell lines towards paclitaxel." (PMID 30737623, 2019). "In vitro studies focusing on the activity of these proteins and ovarian cancer cell invasion might shed more light on whether, and how, the calpain system interacts with Syk/MAP4 to influence patient outcome." (PMID 30737623, 2019).
esophageal squamous cell carcinoma (6 papers, 2018 to 2023). Esophageal squamous cell carcinoma (ESCC) is a type of esophageal carcinoma (EC) that can affect any part of the esophagus, but is usually located in the upper or middle third. "Low MAP4 expression was significantly associated with lower stage (χ2 = 15.857, df = 3, P = 0.001) which agreed with a study of esophageal squamous cell carcinomas (n = 364), where MAP4 expression was linked with tumour stage and lymph node metastasis." (PMID 30737623, 2019). "Overexpression of MAP4 is associated with a poor prognosis of esophageal squamous cell carcinoma and promotes cell invasion and migration through the MAP4-ERK-Jun-VEGF signaling pathway." (PMID 31040780, 2019). "In gastrointestinal cancer, particularly esophageal squamous cell carcinoma, MAP4 has been reported as a therapeutic target and the key regulator of cell invasion and migration." (PMID 38027033, 2023). "Recently, overexpression of MAP4 has been demonstrated to be associated with poor prognosis and promotion of cell invasion and migration through MAP4-ERK-Jun-VEGF signaling in esophageal squamous cell carcinoma." (PMID 29743960, 2018). "Our new findings were consistent with recent studies, which have shown a correlation between MAP4 overexpression and poorer prognostic outcome in bladder cancer and esophageal squamous cell carcinoma." (PMID 29743960, 2018). "Our current findings disclosed a novel FBXW7/MAP4/ERK axis in esophageal squamous cell carcinoma." (PMID 36991467, 2023). "A study determined that FBXW7 deficiency and certain FBXW7 mutations can promote the invasive and migratory capacity of esophageal squamous cell carcinoma (ESCC) cells via MAP4 overexpression and ERK phosphorylation." (PMID 38027013, 2023).
lung adenocarcinoma (6 papers, 2013 to 2025). A carcinoma that arises from the lung and is characterized by the presence of malignant glandular epithelial cells. "Upregulation of microtubule-associated protein 4 (MAP4) expression was also related to tumor invasion and migration, in addition to the worse prognosis of different solid tumors, such as lung adenocarcinoma and breast cancer." (PMID 41317544, 2025). "This study aims to explore the primary mechanism underlying the relationship between MAP4 and radiation resistance in lung adenocarcinoma." (PMID 38341398, 2024). "Univariate Cox regression analysis showed that pT stage, pN stage, pTNM stage and MAP4 expression were all associated with poor OS in patients with lung adenocarcinoma." (PMID 38341398, 2024). "As determined by the CCK8 assay, the results suggested that the silencing of MAP4 is associated with the viability of lung adenocarcinoma cells." (PMID 38341398, 2024). "Both our clinical data and bioinformatic analysis of lung adenocarcinoma showed that increased MAP4 expression in LADC was significantly associated with poorer PFS and OS." (PMID 38341398, 2024). "High expression of MAP4 is associated with poorer overall survival (OS) in patients with lung adenocarcinoma." (PMID 38341398, 2024). "Kaplan‒Meier survival curves showed that high expression of MAP4 was associated with poor OS in patients with lung adenocarcinoma in the overall population (P< 0.0001), training cohort (P = 0.0034) and validation cohort (P < 0.0001)." (PMID 38341398, 2024). "An elevated MAP4 expression in lung adenocarcinoma tissues was associated with differentiation, TNM stage, and pathological T stage." (PMID 35845140, 2022). "Further multivariate regression analysis showed that pT stage (P = 0.048) and MAP4 expression level (P < 0.001) were independent prognostic factors for the overall survival of patients with lung adenocarcinoma." (PMID 38341398, 2024). "MAP4 is involved in the EMT process induced by ionizing radiation, and MAP4 is a potential target molecule that promotes EMT induced by ionizing radiation in lung adenocarcinoma cells." (PMID 38341398, 2024). "Further studies suggested that the downregulation of MAP4 can affect the viability of lung adenocarcinoma cells after irradiation and participate in the radiation resistance of lung adenocarcinoma cells by affecting EMT." (PMID 38341398, 2024). "In summary, our results suggest that MAP4 is overexpressed in lung adenocarcinoma; it worsens the prognosis of LADC by promoting the migration and invasion of lung adenocarcinoma cells." (PMID 38341398, 2024). "The results of immunohistochemical scoring suggested that the expression of MAP4 in lung adenocarcinoma tissue was significantly higher than that in adjacent normal lung tissue (P < 0.001)." (PMID 38341398, 2024). "Immunohistochemical analysis was performed on lung adenocarcinoma tissues and adjacent lung tissues to determine the expression of MAP4 in lung adenocarcinoma tissues." (PMID 38341398, 2024). "We developed a nomogram including clinical factors and MAP4 expression that can be used for prognosis prediction in patients with lung adenocarcinoma." (PMID 38341398, 2024). "The lung adenocarcinoma cell lines A549 and H1299 were used to study the effect of inhibiting MAP4 gene expression on radiosensitivity and to determine its preliminary mechanism related to EMT regulation." (PMID 38341398, 2024). "MAP4 participates in radiation resistance in lung adenocarcinoma by regulating the radiation-induced EMT process." (PMID 38341398, 2024). "The results of in vitro experiments showed that the downregulation of MAP4 significantly affected the migration and invasion of lung adenocarcinoma cells." (PMID 38341398, 2024). "MAP4 plays a crucial role in the development of radioresistance in lung adenocarcinoma by regulating the radiation-induced EMT pathway." (PMID 38341398, 2024).
lung adenocarcinoma (continued). "All the results indicated that patients with high expression of MAP4 in lung adenocarcinoma had poorer overall survival." (PMID 38341398, 2024). "MAP4 expression in lung adenocarcinoma tissues was significantly higher than that in adjacent normal lung tissues." (PMID 38341398, 2024). "Scratch assays and transwell assays were used to explore the effect of MAP4 on the migration and invasion of lung adenocarcinoma cells." (PMID 38341398, 2024). "The purpose of this study was to investigate the level of expression of MAP4 in lung adenocarcinoma (LADC) samples and to evaluate its prognostic value and the influence on cancer progression in LADC patients." (PMID 29743960, 2018). "After expanding the sample size, consistent with our previous findings, we found that MAP4 may act as an oncogene to affect the prognosis of lung adenocarcinoma." (PMID 38341398, 2024). "Finally, the current study only preliminarily confirmed that MAP4 is involved in the radiation resistance of lung adenocarcinoma through EMT, and more research is needed to understand the underlying mechanism." (PMID 38341398, 2024). "There were 151 (55.92%) patients with lung adenocarcinoma who highly expressed MAP4." (PMID 38341398, 2024). "In this study, we hypothesized that MAP4 is an independent prognostic factor and radiosensitizing target in patients with lung adenocarcinoma." (PMID 38341398, 2024). "Likewise, the RT‒qPCR results showed that the expression level of MAP4 in lung adenocarcinoma tissues was significantly higher than that in adjacent normal lung tissues (P < 0.001)." (PMID 38341398, 2024). "MAP4 is highly expressed in lung adenocarcinoma; it may affect prognosis by promoting the migration and invasion of cancer cells." (PMID 38341398, 2024). "Notably, in 515 lung adenocarcinomas, MAP4 protein levels were positively correlated with EMT-related protein levels." (PMID 38341398, 2024). "MAP4 may worsen the prognosis of lung adenocarcinoma by promoting the migration and invasion of lung adenocarcinoma cells." (PMID 38341398, 2024). "MAP4 may serve as a biomarker for the prognosis assessment of lung adenocarcinoma and as a new therapeutic target for improving radiosensitivity." (PMID 38341398, 2024). "MAP4 may serve as a biomarker for lung adenocarcinoma prognosis evaluation and as a new target for improving radiosensitivity." (PMID 38341398, 2024). "MAP4 knockdown efficiently suppresses lung adenocarcinoma cell migration and invasion." (PMID 31040780, 2019). "Therefore, we speculate that MAP4 may be related to the acquisition of radioresistance in lung adenocarcinoma cells during radiotherapy through EMT." (PMID 38341398, 2024). "Bioinformatics analysis, RT‒qPCR, Cell Counting Kit-8 (CCK-8) assays and Western blot experiments were used to study the relationship between MAP4, epithelial–mesenchymal transition (EMT) and radiation resistance in lung adenocarcinoma." (PMID 38341398, 2024). "MAP4 protein levels were positively correlated with EMT-related protein levels in LADC samples from the TCGA database and our clinical tissue samples of lung adenocarcinoma." (PMID 38341398, 2024). "A biomarker set of two genes, the MAP4 and SPP1, provides 99.36% accuracy for differentiating between lung adenocarcinomas and normal lung." (PMID 23369236, 2013). "The results showed that MAP4 staining was stronger in lung adenocarcinoma tissues than in adjacent noncancerous tissues." (PMID 38341398, 2024). "The results of bioinformatics analysis suggested that in the three datasets of 243_g_at, 200836_s_at and 212567_g_at, the expression level of MAP4 was negatively correlated with the progression-free survival (PFS) and overall survival (OS) times of lung adenocarcinoma patients." (PMID 38341398, 2024).
lung adenocarcinoma (continued). "The results of wound healing experiments and transwell experiments in this study showed that the downregulation of MAP4 significantly inhibited the migration and invasion of LADC cells, which confirmed that MAP4 can promote the migration and invasion of lung adenocarcinoma cells once again." (PMID 38341398, 2024). "However, to the best of our knowledge, no study has reported that MAP4 plays a radiosensitizing role in lung adenocarcinoma cells by affecting EMT." (PMID 38341398, 2024).
breast carcinoma (5 papers, 2019 to 2025). "Although the target major isoform of MAP4 has a similar extent of isoform-drug response association and length as the other isoforms, it is highly expressed among breast cancer cell lines." (PMID 31554914, 2019). "Moreover, the expression of MAP4 has been observed in breast cancer cell lines." (PMID 38027033, 2023). "Functional studies were conducted in breast cancer cell lines to evaluate the impact of ARIH1 depletion on microtubule stability, MAP4 regulation, and paclitaxel sensitivity." (PMID 40075632, 2025).
heart failure (5 papers, 2014 to 2025). Inability of the heart to pump blood at an adequate rate to meet tissue metabolic requirements. "Both MAP4 and detyrosination are induced in cardiac hypertrophy and heart failure in patients, implying a potentially causal role in cardiac remodeling." (PMID 33707436, 2021). "Similarly in myocardial samples from patients with heart failure, MAP4 was significantly upregulated, and the levels of detyrosinated microtubules were markedly increased." (PMID 40332117, 2025). "MAP4 microtubule decoration restricts with beta-adrenergic receptor recycling, which might explain beta-adrenergic receptor downregulation in heart failure." (PMID 25519320, 2014). "Supporting the notion that the tubulin network is distorted in heart failure cells, mRNA expression analysis by qPCR confirmed an overall increase in the expression of α1A-tubulin (TUBA1A), β2B-tubulin (TUBB2B), β3-tubulin (TUBB3), γ-1tubulin (TUBG1), and microtubule-associated proteins (MAP4)." (PMID 26725114, 2016). "Recent work examining tissue from the RV of human heart failure patients found a set of genes that are unique to RV failure compared to LV failure: WIPI1, HSPB6, SNAP47 and MAP4." (PMID 31960631, 2020).
bladder cancer (3 papers, 2018 to 2019). "In addition, in the present study, low MAP4 expression was significantly associated with lower grade (χ2 = 22.933, df = 2, P < 0.001) which has also been observed in bladder cancer (n = 34)." (PMID 30737623, 2019). "For instance, the cAMP/PKA pathway is involved in bladder cancer cell invasion by targeting MAP4-dependent MT dynamics." (PMID 31040780, 2019). "Ou and colleagues have reported that the cAMP/PKA signaling pathway is involved with bladder cancer cell invasion by targeting MAP4-dependent microtubule dynamics." (PMID 29743960, 2018). "In addition, the knockdown of MAP4 was found able to markedly inhibit bladder cancer cells invasion." (PMID 30737623, 2019).
neuroblastoma (3 papers, 2018 to 2023). Neuroblastoma (NB) is the most common solid, extracranial childhood tumor. "MAP4, a type of microtubule-associated proteins, was first identified in mouse neuroblastoma cells." (PMID 29743960, 2018). "When full-length MAPs fused with EGFP were expressed in human neuroblastoma (SH-SY5Y) cells, the microtubules in apical regions of protrusions expressing tau were straighter than in cells expressing MAP2 and MAP4." (PMID 37258650, 2023).
prostate carcinoma (3 papers, 2015 to 2022). A carcinoma that arises from epithelial cells of the prostate gland. "In terms of prostate cancer, MAP4 is also considered a potential biomarker for cancer detection and discrimination between prostate tumors with different malignancy and aggressiveness." (PMID 35845140, 2022). "In prostate cancer, MAP4 was also reported to be a potential biomarker for detection of prostate cancer and discrimination between prostate tumors with different malignancy and aggressiveness." (PMID 29743960, 2018).
Alzheimer disease (2 papers, 2011 to 2025). A progressive, neurodegenerative disease characterized by loss of function and death of nerve cells in several areas of the brain leading to loss of cognitive function such as memory and language. "Mtap4 encodes isoforms of MAP4 with differing microtubule-stabilization properties that have been proposed to regulate the dynamic behaviors of extending neurites, structures lost or altered in the earliest stages of Alzheimer's disease." (PMID 21867878, 2011).
cardiac hypertrophy (2 papers, 2011 to 2021). "Certainly MAP4 plays a critical role in stabilization of microtubules during pressure overload cardiac hypertrophy and associated contractile dysfunction." (PMID 21829519, 2011).